FEZ1 (fasciculation and elongation protein zeta 1)
Diseases named in the same sentence as FEZ1 in open-access papers (continued):
Sharing a sentence is not in itself a finding about the gene and the disease.
tumor (15 papers, 2002 to 2025). "FEZ1 is frequently altered in human cancers, and its expression affects cell growth by regulating mitosis, which in turn inhibits tumor formation in vivo." (PMID 40746884, 2025). "Simultaneous infection of stromal and tumor cells; Upregulation of Fez1 and Pycard; Downregulation of DLL-4, Angiopoietin 2, PECAM, Tie-1, and FOS EGR2, CREB-5, IL-6, Map2K1, CCL22, TIMD4 and CCL19." (PMID 35640930, 2022). "For instance, FEZ1 (also known as LZTS1) is a tumor suppressor gene located at 8p22, a region frequently deleted in human tumors." (PMID 29435136, 2018). "For example, FEZ1/LZTS1 (Leucine zipper putative tumour suppressor 1) is a tumour suppressor gene important for cell cycle control." (PMID 22412920, 2012). "The FEZ1 gene was mapped to chromosome 8p22 (a common aberration in human tumours)." (PMID 36936167, 2023). "To determine whether GAP43 and FEZ1 are simply required for tumor growth in vivo, we transplanted Gap43 and Fez1 knock-down cells subcutaneously and quantified tumor growth." (PMID 31833833, 2019). "The 8p22 region identified in our GBCs spans the FEZ1/LZTS1 gene, a candidate TSG, whose expression is altered in multiple human tumours." (PMID 12177780, 2002). "Several candidate tumor suppressor genes have been identified from 8p including DLC-1 (8p21.3-22), FEZ1 (8p22), liver-related putative tumor suppressor (LTPS) gene (8p23), PCM1(encoding a centrosomal protein) and DUSP4/MKP-2 (encoding a MAP kinase phosphatase)." (PMID 17784942, 2007). "One case showed a substantial reduction of expression with 60% of the tumor cells negative, while the remaining four showed diffuse positivity for Fez1 immunostaining." (PMID 15357873, 2004).
cancer (14 papers, 2004 to 2025). A tumor composed of atypical neoplastic, often pleomorphic cells that invade other tissues. "Mutations in the FEZ1 gene have been found in a variety of cancers." (PMID 36936167, 2023). "To investigate the expression pattern of FEZ family in different cancer types, we searched Oncomine online website and found FEZ1 and FEZ2 were both upregulated in different cancer types." (PMID 35036176, 2022). "Quantification of GFPpositive cancer cells in the liver by flow cytometry documented a significant reduction in metastatic seeding by SCLC cells with Gap43 or Fez1 knocked-down." (PMID 31833833, 2019). "Recent studies have shown that the introduction of FEZ1 into Fez1 null cancer cells reduced cell growth with the accumulation of cells at late S to G2/M phase of the cell cycle." (PMID 15357873, 2004). "FEZ1 is located at chromosome 8p22 in a region deleted in many cancers, including 42% of UCC." (PMID 22412920, 2012). "Both FEZ1 and FEZ2 showed dysregulation in many cancer types, but only few types of cancer showed an upregulation of FEZ2, which including PDAC." (PMID 35036176, 2022). "Recently we identified a new player: FEZ1/LZTS1 that contributes to the fine-tuning of the molecular events that determine progression through mitosis, and here will review its role in cancer development and in M phase regulation." (PMID 17718912, 2007).
infection (3 papers, 2018 to 2022). The state of being infected such as from the introduction of a foreign agent such as serum, vaccine, antigenic substance or organism. "Subsequent studies uncovered the underlying mechanisms by which HIV-1 locally controls FEZ1 activity to promote early infection." (PMID 34229718, 2021). "Although kinesin-1 is normally an outward motor, capsid-bound FEZ1 regulates the balance of motor activity to ensure net forward movement to the nucleus for efficient infection." (PMID 34229718, 2021). "In order to confirm that the genes induced when there was overexpression of FEZ1 would not be activated when FEZ1 was depleted, and therefore showing that FEZ1 was indeed responsible for determined gene induction, we generated fez1‐knockdown U87 cells using shRNA lentiviral infection." (PMID 29321952, 2018).
neurodevelopmental disorder (1 paper, 2023). A behavioral and cognitive disorder with onset during the developmental period that involves impaired or aberrant development of intellectual, motor, or social functions. "Our transcriptomic analysis strongly suggested that FEZ1 expression is closely coupled to expression of SNARE complex proteins also implicated in neurodevelopmental disorders." (PMID 37746155, 2023).
FEZ1 also shares sentences with these, for which no sentence is quoted: autism (1 paper); bipolar disorder (1); cervical cancer (1); infantile epilepsy (1); Lissencephaly (1); malignant glioma (1); Parkinson disease (1); primitive neuroectodermal tumor (1); prostate carcinoma (1); Stroke (1).